MET (MET proto-oncogene, receptor tyrosine kinase)
Diseases named in the same sentence as MET in open-access papers (continued):
Sharing a sentence is not in itself a finding about the gene and the disease.
cancer (continued). "HGF-induced activation of MET signaling axis has been reported to be involved in the progression of various cancers by upregulation of proliferation, invasive activity, motility, and anti-apoptotic activity." (PMID 40076928, 2025). "The results suggested the significance of HGF-targeted therapy in cancer treatment and overcoming the resistance of MET inhibitor." (PMID 40299447, 2025). "Together, these findings uncover a previously unrecognized layer of MET regulation with potential implications for the development of selective therapies targeting MET-driven cancers." (PMID 41383124, 2025). "Understanding how its product, c-MET, functions and the ways it can become overactive in cancer cells is essential for developing new targeted treatments." (PMID 40361420, 2025). "Alterations that give rise to MET’s transforming potential vary extensively and appear to correlate with cancer type." (PMID 39858062, 2025). "For instance, following EGFR signaling inhibition, cancer cells often increase the expression and activation of alternative receptors such as MET or IGF-1R, thus activating bypass survival pathways and acquiring therapeutic resistance." (PMID 40872476, 2025). "c-MET, a receptor tyrosine kinase that induces a wide range of biological pathways involved in cancer growth, is overexpressed in many types of cancers." (PMID 40369167, 2025). "Our study describes the first isolation and characterization to our knowledge of mAbs that cross-react with MET in cancer patients." (PMID 40401526, 2025). "Aberrant activation of the HGF/c-MET axis has been shown to play a critical role in the development and progression of various human cancers and is often associated with poor clinical outcome and drug resistance." (PMID 40520181, 2025). "Hepatocyte growth factor (HGF) is a multifunctional growth factor known to induce the progression of various cancers through the specific tyrosine kinase receptor MET." (PMID 40299443, 2025). "In summary, our pan-cancer analysis of TCGA data identified MET as exhibiting the highest expression level in THCA among all cancer types." (PMID 41233563, 2025). "c-MET also plays an important role in cancer cell survival by promoting anti-apoptotic signals and protecting cells from oxidative stress by activating the NRF2 pathway." (PMID 40369167, 2025). "Increased phosphorylation of MET was observed in cancer cells (inset: T), whereas MET phosphorylation was downregulated in non-malignant liver tissue (inset: N)." (PMID 40076928, 2025). "Hepatocyte growth factor (HGF) is a multifunctional growth factor and is reported to have an important role in the progression of various cancers through the activation of MET, which is a specific receptor of HGF." (PMID 40299447, 2025). "MET and its ligand, hepatocyte growth factor (HGF), are observed in most solid tumors, and signaling via MET is known to be associated with a number of malignant tumors." (PMID 40004241, 2025). "Somatic events involving MET have also been described in NSCLC and other cancers, with the most common being exon 14 deletion mutations that result in loss of the juxtamembrane regulatory domain." (PMID 39858062, 2025). "Simultaneously, the improper activation of PI3K/AKT/mTOR, c-MET, Gal-l and NF-κ B implies higher proliferation activity of the cancer cells, dysregulated autophagy and hinders apoptosis." (PMID 40022036, 2025). "NGS targeting 54 cancer related genes, including assessments for copy number variants in EGFR, ERBB2, and MET." (PMID 40867329, 2025). "In cancer cells, HGF secreted either by cancer cells themselves or by surrounding stromal tissue induces the phosphorylation of c-MET." (PMID 41289612, 2025). "We screened patients with lung (n = 25) and breast (n = 75) cancer and found that 13% had antibodies binding to both the recombinant ectodomain of MET, and the ligand binding part of MET, SEMA." (PMID 40401526, 2025).
cancer (continued). "It is thought that there is potential for preventing the metastasis and progression of cancer cells inhibiting the MET signaling pathway and inducing apotosis in several cancer types." (PMID 40728965, 2025). "HGF exerts its biological functions by triggering a cascade of downstream signaling pathways through its receptor, c-MET, which plays a significant role in various types of cancers." (PMID 40520181, 2025). "Current studies predominantly rely upon patient-derived xenografts (PDXs) or humanized mouse models that express HGF to study MET-positive cancers and MET-targeting therapeutics." (PMID 39858062, 2025). "Genetic silencing of MET markedly attenuated cancer cell migration capacity, concomitant with downregulation of epithelial–mesenchymal transition (EMT)-related signaling molecules and diminished activation of both STAT3 and ERK pathways." (PMID 41233563, 2025). "A number of preclinical research has also shown that MET TKIs are capable of attenuating proliferative signal transduction of cancer cells with normal MET and MET amplification." (PMID 41368576, 2025). "This underlines the growing interest and potential of therapies targeting MET in various malignant tumours." (PMID 39374163, 2025). "By summarizing the current knowledge on c-MET-related dysregulations in various cancers, we aim to provide a clear picture of c-MET as a target for cancer therapies." (PMID 40361420, 2025). "Both downstream activation through alternative pathways and upstream activation occurs after inhibition of KRAS G12C, which correlates with the increased expression levels of EGFR, HER2, FGFR, and c-MET observed in cancer cells." (PMID 40597785, 2025). "HGF is secreted into the tumor microenvironment, where it binds to the MET proto-oncogene/receptor tyrosine kinase receptor on cancer cells to activate MET signaling." (PMID 40723207, 2025). "Primary and acquired resistance to EGFR inhibition have been directly linked to overexpression of MET, and it is well established that EGFR and MET share similar pathway trajectories and phenotypical outcomes in cancer." (PMID 41115375, 2025). "Our study unveils ISR as a pivotal regulator of MET oncogene overexpression in cancer, highlighting a novel layer of translational control that modulates HGF/MET-driven invasive growth." (PMID 39774381, 2025). "This study highlights a new level of MET oncogene expression control in cancer and establishes a pivotal mechanistic connection between the integrated stress response pathway and invasive growth." (PMID 39774381, 2025). "Activation of the HGF/MET signaling axis promotes cancer cell proliferation, anti-apoptosis, motility, invasiveness, and resistance to therapeutic agents." (PMID 40299443, 2025). "In oral cancer, it was suggested that the MET activation may represent an early driver in oral premalignancy and may be target for chemoprevention of oral cancer, and the c-met was identified as a potential prognostic marker of cancer risk in patients with oral leukoplakia 12, 15-17." (PMID 39991569, 2025). "c-Met mRNA and protein overexpression has been described in many varieties of human cancers, and its role in MET signaling is essential for cancer stemness and poor prognosis." (PMID 39815326, 2025). "Cancer progression is significantly influenced by aberrant signaling through receptor tyrosine kinases (RTKs), including c-MET, EGFR, VEGFR, PDGFR, HER2/HER3, and FLT3." (PMID 39924521, 2025). "Our study’s findings are consistent with existing evidence regarding c-MET overexpression in other cancer types." (PMID 40078386, 2025). "As a result, the HGF/c-MET pathway has emerged as a significant therapeutic target in various cancers." (PMID 40520181, 2025). "In PCa, MET overexpression correlates with cancer progression, metastasis to bone and lymph nodes, and castration resistance." (PMID 40723207, 2025).
cancer (continued). "miR34a targets multiple oncogenic genes, such as Cluster of Differentiation 44 (CD44) and Mesenchymal–Epithelial Transition factor (c-MET), by suppressing cell proliferation, metastasis, and cancer growth." (PMID 41150792, 2025). "Antibody–drug conjugates (ADCs) have also been developed, such as telisotuzumab-vedotin, which is a combination MET antibody and anti-microtubule drug that has shown potential benefit in clinical trials for patients with MET-positive cancers." (PMID 39858062, 2025). "In regard to aging-related proteins, MET codes for c-Met protein and is a known proto-oncogene involved in many cancers." (PMID 40940954, 2025). "On the other hand, MET is a proto-oncogene that has been extensively studied for its role in cancer." (PMID 40842627, 2025). "Researchers have also tried to knock down amplified MET in these cells using siRNA, and cancer cells retained their sensitivity to sotorasib, indicating the importance of MET amplification as an off-target resistance to KRAS inhibitors." (PMID 40597785, 2025). "Studies have demonstrated that knockdown of c-MET induces apoptosis in multidrug-resistant cancer cell lines, underscoring its potential as a promising therapeutic target." (PMID 40520181, 2025). "This concept highlights both the widespread MET overexpression in cancer and its role in cancer progression." (PMID 39774381, 2025). "Lately, bispecific antibody drug conjugates targeting EGFR and MET have also attracted attention in the pharmaceutical industry with multiple drugs of this kind already in early phase trials for MET-aberrant cancers." (PMID 41368576, 2025). "MET’s role in cancer was initially identified in a chemical mutagenesis screen of a human osteosarcoma cell line, which yielded a fusion protein with transforming potential." (PMID 39858062, 2025). "This review explores MET dysregulation in cancer, the available treatment options for MET-driven cancers, and the mechanisms that lead to resistance to these therapeutics." (PMID 39858062, 2025). "Further examination and analysis using the annexin-v binding assay and immunoblotting analysis found that cancer cells with MET amplification are more dependent on the HGF/c-MET signaling pathway for oncogenic growth." (PMID 40361420, 2025). "The emerging group of anti-c-MET CAR-T cells has exhibited remarkable efficacy against cancer cells with c-MET overexpression." (PMID 39664377, 2024). "In conclusion, the intricate interplay between c-MET, targeted therapy, and immunotherapy offers promise in cancer treatment." (PMID 39664377, 2024). "When MET amplification occurs in cancer cells already treated with targeted therapies, it can lead to treatment resistance." (PMID 38675409, 2024). "Since the failure of these mAbs against MET, many tyrosine kinase inhibitors (TKIs) against MET have been developed for various types of cancers, including GC." (PMID 38892160, 2024). "MET kinase inhibitors and MET-targeting monoclonal antibodies each offer distinct therapeutic benefits and limitations in treating MET-dependent cancers." (PMID 39598385, 2024). "Several studies have consistently used FISH to define MET amplification, and recent trials of MET inhibitors for MET-amplified cancers have been successful." (PMID 38892160, 2024). "In both cases, i.e., in the presence or the absence of INF-γ, MET-targeting treatment is sufficient to diminish PD-L1 levels, suggesting that cancer immune evasion can be limited by blocking MET signaling." (PMID 38892318, 2024). "Overexpression of c-MET and HGF is associated with poor prognosis or metastatic progression in several major cancers." (PMID 39335535, 2024). "c-MET is often aberrantly activated in cancer, leading to the persistent activation of several downstream signaling pathways, including the mitogen-activated protein kinase (MAPK) and phosphatidylinositol 3-kinase (PI3K)-AKT pathways." (PMID 39065771, 2024).
cancer (continued). "One year later, the great diversity of MET exon 14 alterations was proved by next-generation sequencing (NGS) across several advanced cancers, including lung, gastric, colorectal, and brain cancers." (PMID 38652103, 2024). "The oncogenic activation of MET drives aggressive behavior including cancer cell proliferation, survival, scattering, epithelial-to-mesenchymal transition, invasion, and metastasis." (PMID 39742369, 2024). "In the context of cancer, the MET oncogene contributes to tumorigenesis, metastasis, and therapeutic resistance, positioning the HGF/MET axis as a significant target for the development of novel anti-cancer therapies." (PMID 39598385, 2024). "It is reported that c-MET can be recognized as a tumor-associated antigen (TAA) by CD8+ T cells, triggering the activation of the immune system against MET-overexpressing cancer cells." (PMID 39201787, 2024). "The rationale behind the enhanced efficacy of such combinations stems from the notion that MET can protect cancer cells from the DNA damage induced by chemotherapeutic drugs." (PMID 38957115, 2024). "Yet, the mechanisms by which GPCRs and EGFR are connected to the oncogenic potential of MET signaling in cancer cells are not fully understood." (PMID 39769452, 2024). "Telisotuzumab effectively blocks both HGF-independent constitutive and HGF-dependent c-MET signaling, leading to apoptosis in cancer cells dependent on amplified c-MET signaling." (PMID 39664377, 2024). "The MET signaling pathway has been predominantly described in cancer, and a key role is the promotion of cell survival." (PMID 38300257, 2024). "The HGF/c-MET pathway serves a critical role in cancer and is an attractive therapeutic target for cancer therapy." (PMID 38763973, 2024). "The formation or disruption of the MET-integrin complex has significant functional implications for cancer cell behavior." (PMID 39769452, 2024). "The intricate interplay between the galectin family and c-MET signaling represents a significant frontier in cancer research and therapy." (PMID 39664377, 2024). "The researchers identified THEMIS2 as a novel regulator of cancer stemness and chemoresistance by disrupting the interaction between PTP1B and p-MET, thus promoting MET signaling in cancer cells." (PMID 38175687, 2024). "MST1R, a homologue of MET, orchestrates cell signaling pathways that foster tumorigenesis, cancer cell survival, and growth." (PMID 39210450, 2024). "MET-specific inhibitors capmatinib and tepotinib have received FDA approval for the treatment of cancers harboring this category of MET alterations." (PMID 38966170, 2024). "This review provides a comprehensive analysis of MET’s interactome, highlighting its role in cancer progression and therapy resistance; (iii) current MET-targeted therapies face challenges due to the receptor’s ability to form compensatory signaling networks." (PMID 39769452, 2024). "Several MET-targeting agents, including MET antibodies and small-molecule kinase inhibitors, are currently envisaged as anti-cancer therapeutics." (PMID 39598385, 2024). "ARGX-111 is an antagonistic anti-c-MET antibody devoid of fucose, known for its robust anti-cancer efficacy due to enhanced antibody-dependent cellular cytotoxicity." (PMID 39664377, 2024). "In NSCLC, MET exon 14 mutations or amplifications are significant predictors of reduced survival, reflecting the aggressive nature of MET-driven cancer phenotypes." (PMID 38675409, 2024). "The discovery and subsequent research on the MET oncogene’s role in cancer onset and progression have illuminated crucial insights into the molecular mechanisms driving malignancy." (PMID 38675409, 2024). "This suggests that MET’s role in resistance extends beyond individual receptors, potentially affecting a range of ErbB-driven cancers, and underscores the necessity of targeting this pathway in combination treatment strategies." (PMID 39769452, 2024).
cancer (continued). "Overall, the research underscores the pivotal roles of galectins—such as Gal-7, Gal-4, and Gal-3—and c-MET signaling in cancer progression." (PMID 39664377, 2024). "In cancer cells characterized by MET amplification, Interferon-gamma (INF-γ) treatment elicits intracellular signaling involving the JAK-Stat pathway that further induces the expression of PD-1 ligands." (PMID 38892318, 2024). "Once activated by its ligand, MET promotes the cell proliferation, survival, and metastatic ability of cancer cells." (PMID 38338342, 2024). "Despite the numerous deregulations described previously, no direct causal link between MET and cancer progression was evidenced until 1997, when MET-activating mutations were found in HPRC and associated with cancer progression." (PMID 38652103, 2024). "Then, we observed that the expression of TRAF1 and TYK2 was lower in the cancer tissues than in the adjacent tissues, however, the expression level of MET is the opposite." (PMID 38363947, 2024). "The rationale for combining c-MET inhibitors with immunotherapy is rooted in the desire to bolster the efficacy of cancer treatment by addressing multiple facets of cancer biology and immune responses." (PMID 39664377, 2024). "Subsequently, the LUAD marker genes NAPSA, NKX2-1, the LUSC marker genes TP63, KRT5, as well as EPCAM and MET were adopted to identify the cancer cell clusters." (PMID 38382091, 2024). "Significant responsiveness to TR1801-ADC was revealed in vivo studies of several xenograft models generated using cancer cell lines with low-to-medium c-MET expression, even at a single dose." (PMID 39664377, 2024). "Although several studies have shown EpCAM+ CTCs as prognostic biomarkers in different cancer types, very few studies have evaluated c-MET expression in CTCs." (PMID 38238761, 2024). "MET, a critical tyrosine kinase, played a vital role in the initiation and progression to drive cancer development by enhancing cell proliferation, morphogenesis, and survival." (PMID 38893622, 2024). "A Phase Ib trial commenced to assess ARGX-111’s potential in treating advanced cancers marked by c-MET overexpression." (PMID 39664377, 2024). "Overall, the promising results from these studies highlight the significant clinical potential of c-MET-targeting ADCs, paving the way for their continued development and potential approval as targeted cancer therapies." (PMID 39664377, 2024). "Activated CAFs secrete HGF, inducing MET activation in cancer cells, and these respond by increasing Tenascin (TNC) secretion." (PMID 38892318, 2024). "Although currently available MET-targeted agents show therapeutic potential for patients with specific types of MET-driven cancers, further research is necessary to develop strategies to overcome the significant toxicity of MET inhibitors." (PMID 38892160, 2024). "This cancer highly expresses MET and AXL, and the combination of NPS-1034 with the commonly prescribed anti-PDAC chemotherapies oxaliplatin and fluorouracil shows a remarkably effective synergistic effect." (PMID 39000029, 2024). "Other ADCs, such as SHR-A1403 and MYTX-011, have been developed and demonstrated enhanced efficacy and safety compared to existing small-molecule inhibitors or monoclonal antibodies targeting MET-overexpressing cancers." (PMID 39598385, 2024). "Functionally, the key feature of the HGF receptor c-MET is the facilitation of scattering, proliferation, and branching morphogenesis in development, tissue regeneration and cancer." (PMID 39580452, 2024). "These advancements underscore the diverse strategies and promising outcomes in addressing cancer through targeting the HGF/c-MET pathway." (PMID 39664377, 2024). "A potential therapeutic strategy involves inducing MET intramembrane proteolysis in cancer cells that overexpress the MET receptor." (PMID 39598385, 2024).